ECM1 (extracellular matrix protein 1)
Diseases named in the same sentence as ECM1 in open-access papers (continued):
Sharing a sentence is not in itself a finding about the gene and the disease.
tumor (continued). "Current studies only show that high levels of ECM1 are detected in the plasma of tumor patients, but the function of ECM1 in tumor interstitial microenvironment is not yet reported." (PMID 36145166, 2022). "Compared with control group, silencing of ECM1 did not postpone tumor formation while retarded the growth of the tumor and increased the sensitivity to drugs." (PMID 36145166, 2022). "In line with the current advances in tumour immunology, our data may suggest that RAS-like PTC with FAL1 and ECM1 upregulation proceeds from carcinogenesis to aggressive PTC by an immunological mechanism compared to classical BRAF-like PTC." (PMID 34203279, 2021). "Our qRT‐PCR results revealed that the expression levels of TNFSF10 (p < 0.01), ECM1 (p < 0.01), and RNF213 (p < 0.01) were significantly increased in advanced LUAD tumor cells, whereas the expression of SCGB3A2 (p < 0.01), SCGB3A1 (p < 0.01), and SFTPC (p < 0.01) was increased in early LUAD." (PMID 33783985, 2021). "A selection of the proteins from this panel are of high abundance in plasma (i.e., C3 and SERPINA1), while others are not (i.e., PF4 and ECM1), and so reflect the contributions of localized changes due to tumor presence and anti-tumor immunity." (PMID 35008327, 2021). "The mean normalized expression level of ECM1 mRNA in tumor specimen was statistically higher than that in non-cancerous counterparts (Mann–Whitney test, P <0.01)." (PMID 24779890, 2014). "The difference in the rate of ECM1 expression between tumor tissue (54/77, 70.1%) and the non-cancerous counterparts (6/77, 7.8%) was statistically different (χ2 = 62.91, P <0.001)." (PMID 24779890, 2014). "Differences in LMVD between the ECM1-positive cases and ECM1-negative cases were statistically significant for both the tumor tissues (Mann-Whitney test, P = 0.045), and the lymph nodes (Mann-Whitney test, P < 0.001)." (PMID 22284579, 2012). "The ECM1 positive staining rates among tumor tissue (31, 75.6%), normal breast tissue (4, 9.8%) and lymph nodes (13, 31.7%) were significantly different (χ2 = 39.08, P < 0.01)." (PMID 22284579, 2012). "We evaluated whether correlations exist between expression of ECM1 or VEGF-C and the clinicopathological characteristics of the disease, (i.e. age; histological type or grade; tumor size; lymph node, ER, and PR status and Her-2/neu score)." (PMID 22284579, 2012). "In two of the cases, we found that the primary tumor was ECM1 negative, whilst ECM1 was expressed in the corresponding lymph node metastases." (PMID 22284579, 2012). "Similarly, the proliferation‐promoting effect of ECM1 on tumor cells was not blocked by RTK inhibitors." (PMID 39563492, 2025). "Similar results were observed in intratibial and subcutaneous tumors in mice, suggesting that ECM1 may promote tumor resistance by activating AR bypass pathways rather than by reactivating the AR itself." (PMID 39563492, 2025). "Compared to cells in tumor 3 that expressed increased epithelial markers like CDKN2A, CRB3, KRT13, and KRT6, tumor cells in metastatic LN exhibited high expression of mesenchymal markers like CDH3, ECM1, TGFB1, WARS, and VIM, indicating that tumor metastasis was related to EMT." (PMID 36569924, 2022). "ECM1 can bind to integrins on the cell surface and then bind to the N-terminal domain of focal adhesion kinase (FAK) to activate FAK, which can inhibit tumor cell apoptosis by mediating the Akt pathway, promote tumor cell surface adhesion, and activate phosphatidylinositol-3-kinase (PI3K)." (PMID 35814477, 2022). "Instead, tumor-specific and context-dependent activation of subset of genes with distinct functions (e.g., SPARC, FN1, MMP7, ZEB1, ECM1) synergistically promoting, for example, collective cell migration upon interaction with the stromal microenvironment, may represent a more likely scenario." (PMID 34036938, 2021).
tumor (continued). "Extracellular matrix protein 1 (ECM1), a classical tumour antigen with intrinsic characteristics of overexpression on tumour cell surface to facilitate the recognition of immune cells, could be a good target for therapeutic tumour vaccines." (PMID 33910591, 2021). "ECM1 was significantly upregulated in tumor tissues compared with non-tumorous tissues." (PMID 30984243, 2019). "ECM1 is known to interact with the EGF domain on other proteins, such as perlecan, and perlecan may induce heparin-binding growth factor responses, including the fibroblast growth factor 2 (FGF2) response, and thereby promote tumor growth." (PMID 25499743, 2014). "Although ECM1 expression may have prognostic significance, not much is known about the regulation of ECM1 expression or the mechanisms of its effect on tumor prognosis." (PMID 24023917, 2013). "Additionally, we found two cases that were ECM1-negative in the primary tumor, but ECM1-positive in the corresponding lymph node metastases." (PMID 22284579, 2012). "However, ECM1 staining was not correlated with tumor size, lymph node status, PR status or the Her-2/neu score (Fisher's exact test, P > 0.05)." (PMID 22284579, 2012). "The identification of Autotaxin and Ecm1 as genes upregulated by activation of this pathway, together with VEGF suggests that deregulation of Wnt/β-catenin signalling during tumour initiation and progression may be one of the factors which promotes tumour angiogenesis." (PMID 15642117, 2005). "Higher ECM1 and VEGF-C mRNA expression levels were also detected in the tumor tissues, compared to the non-cancerous tissue types or lymph nodes (P < 0.05)." (PMID 22284579, 2012).
cancer (70 papers, 2009 to 2026). A tumor composed of atypical neoplastic, often pleomorphic cells that invade other tissues. "The EVs of the two complex carcinoma cell lines shared 487 over-represented proteins, mostly associated with angiogenesis, cell migration, adhesion and motility (ECM1, EDIL3, VEGFC)." (PMID 39462388, 2024). "Recent findings suggest that ECM1 is associated with cancer cell migration, invasion, adhesion, and angiogenesis." (PMID 36145166, 2022). "ECM1 is associated not only with cisplatin resistance of cancer cells, but also with the malignant transformation of NFs into CAFs." (PMID 36145166, 2022). "Moreover, increased levels of ECM1 in the sera of BC patients have been associated with cancer recurrence and poor long-term survival." (PMID 38402239, 2024). "In this study, we show that high expression of extracellular matrix protein-1 (ECM1) promotes cancer cell cisplatin resistance, and the secreted ECM1 activates normal fibroblasts (NFs) to transform cells with characteristics of cancer-associated fibroblasts (CAFs)." (PMID 36145166, 2022). "ECM1 supports cancer stem cell maintenance by enhancing β-catenin signaling, thereby promoting epithelial-mesenchymal transition (EMT) and drug resistance." (PMID 41000875, 2025). "RNA-seq data showed that ECM1 was downregulated in cancer samples and was a DIU gene in three LGC cancer samples." (PMID 37741817, 2023). "The overexpression of ECM1 has now been incorporated into scoring models to suggest poor clinical prognosis and metastatic potential in several types of cancer patients." (PMID 36765767, 2023). "There is also a study demonstrating that ECM1 plays an important role in cancer metastasis by stabilizing β-catenin." (PMID 37872487, 2023). "PCR validation showed that the expression of ECM1b was significantly depleted in cancer samples, while ECM1a had a similar expression level in both cancer and normal samples, leading to an overall depletion of ECM1 in cancer samples." (PMID 37741817, 2023). "Extracellular matrix protein 1 (ECM1) is a secreted glycoprotein that is predominantly expressed in the perivascular area but is also significantly elevated in many malignant epithelial tumors that produce metastasis." (PMID 37872487, 2023). "Most of the early functional studies on ECM1 are focused on bone and cartilage development, skin formation, and angiogenesis, other than malignancies." (PMID 36145166, 2022). "Together, these data thus confirmed that ECM1 can serve as a regulator of cell cycle progression and apoptotic death in this cancer type." (PMID 35574325, 2022). "In the present study, we confirmed that ECM1 was overexpressed in CRC cancer tissues and cell lines." (PMID 35574325, 2022). "A great number of studies have indicated that ECM1 can accelerate cancer development and invasion, and ECM1 overexpression has been identified as a poor prognosis indicator." (PMID 35402261, 2022). "Another study demonstrated that cancer cells secrete ECM1, which, through a feedback loop, induces a NOTCH-mediated endothelial cell promotion of cancer progression by enhancing migration and invasion." (PMID 35884405, 2022). "Emerging evidence has revealed that ECM1 is upregulated in many cancers and contributes to a worse patient prognosis." (PMID 36408224, 2022). "Focal amplification peaks, including the well‐studied cancer‐driven gene MYC (8q.24.21) and several antiapoptotic genes (MCL1, HORMAD1, and ECM1 on 1q21.2), were identified in the high‐risk patients, along with a focal deletion peak at 13q14.2." (PMID 34894177, 2022). "Among other genes, SRSF6 modulates alternative RNA splicing of the genes OGDHL (oxoglutarate dehydrogenase-like protein) and ECM1 (extracellular matrix protein 1), both known to play roles in cancer metastasis." (PMID 34769047, 2021). "ECM1 controls cancer stem cell-like properties and epithelial-to-mesenchymal transition through stabilization of β-catenin expression." (PMID 34244494, 2021).
cancer (continued). "Recent progress has highlighted the importance of noncellular components, especially the extracellular matrix 1(ECM1), during cancer progression." (PMID 32157214, 2020). "Invadopodia, actin-rich protrusive structures developed at cancer cells surface in order to degrade the surrounding ECM1–3, are correlated to the metastatic potential of diverse cancer types, hence the importance of better understanding their biology." (PMID 32321993, 2020). "Two genes, KRT17 and ECM1, which expression was elevated in our TERTp(+) PTCs, demonstrated higher expression in a variety of cancer types." (PMID 32560331, 2020). "Higher EV protein levels detected here as well as previous links to more aggressive cancer phenotypes suggest that ECM1 is an interesting target for further study." (PMID 27770278, 2017). "Fibronectin (FN1) and extracellular matrix protein 1 (ECM1) are two members of this class that have been previously shown to correlate with the metastasis of other cancer cells." (PMID 27014972, 2016). "In most cancers, ECM1 was found to promote cancer progression and invasion, and overexpression of ECM1 has been identified as an indicator of poor prognosis." (PMID 27460906, 2016). "High levels of ECM1 expression are detected in aggressive tumorigenic cancer cell lines MDA-MB-435 and LCC15, and in human carcinomas, including those of the lung, prostate, colon and breast, and especially in ductal breast carcinomas." (PMID 25499743, 2014). "ECM1 expression correlates adversely with patient outcome in several types of cancer, and ECM1 was expressed at relatively high levels in BT-474 TR cells, at both the mRNA and protein levels." (PMID 25499743, 2014). "Overall, the average frequency of ECM1 positivity in carcinomas was 75%, which is much higher than that of epithelial hyperplasia (11.7%) or normal tissues (7.1%)." (PMID 24023917, 2013). "Multiple comparison (χ2 division, α = 0.0125) analysis showed the ECM1 positive staining rate in cancer tissue was higher than in normal tissue and the lymph nodes (P < 0.001)." (PMID 22284579, 2012). "ECM1 is overexpressed in various malignant epithelial tumors, and has been identified as a marker of poor clinical prognosis." (PMID 22284579, 2012). "Within the draining lymph nodes, ECM1 staining was specific for the metastatic cancer cells and occurred primarily in their cytoplasm." (PMID 22284579, 2012). "WA targets the NF-κB/ECM1 signaling pathway, involved in cancer cell survival and drug resistance." (PMID 39949780, 2025). "Reports also demonstrated that ECM1 could activate or inhibit the activity of MMP9 in different cancers and genodermatosis." (PMID 38546916, 2024). "In fact, the role of ECM1 in cancer metastasis has been well-documented." (PMID 38402239, 2024). "Consequently, BC cells secrete more ECM1 protein, which promotes cancer cell invasion and migration." (PMID 38402239, 2024). "The secreted ECM1 acts on the cancer cells to promote invasion and migration." (PMID 38402239, 2024). "Extracellular matrix protein 1 (ECM1) has been associated with cancer but the underlying molecular mechanisms are not clear." (PMID 34244494, 2021). "Previous research suggested that ECM1 plays pivotal roles in cancer cell migration and invasion, so we examined whether ECM1 affected the migration and invasion ability of the GC cells." (PMID 30984243, 2019). "ECM1 plays a key role in lymphangiogenesis, which could be an inducement of cancer invasion and metastasis." (PMID 28232943, 2017). "The present study demonstrates that ECM1 may regulate both cancer cell proliferation and Ttzm resistance through interaction with EGF signaling." (PMID 25499743, 2014). "ECM1 expression is also correlated with poor prognosis and metastatic potential in cancer." (PMID 25499743, 2014).
cancer (continued). "Underlying these processes, cancer cells overexpressing FSTL3 exhibited increased expression of the genes associated with epithelial-mesenchymal transition (Vim, Zeb-1, Snai1/2) and extracellular matrix organization (Ecm1), while expression of epithelial markers (Epcam, Cdh1) decreased." (PMID 41029436, 2025). "However, the detailed molecular mechanism associated with ECM1-mediated signaling in cancer cells is not quite clear." (PMID 34244494, 2021). "Because commercial antibodies against ECM1 could not be used for IHC to identify the expression differences among ECM1 subtypes in cancer tissues, we ordered three custom rabbit polyclonal antibodies to identify the protein expression differences of the ECM1 subtypes." (PMID 34244494, 2021). "Similarly, we found that LA/DC-CTL could generate remarkable cytotoxicity against HLA-A2.1+/ECM1+ primary cancer cells and microtissue blocks derived from fresh clinical specimens." (PMID 33910591, 2021). "Some reports have suggested that elevated levels of ECM1 and MBL2 play important roles in cancer development and progression, implying their prospective utility as biomarkers for identifying high‐risk patients and as prognostic tools for clinicians." (PMID 40545963, 2025). "The mechanism was mediated through ECM1 and MMP9 activation, genes known for cancer invasiveness and aggressiveness." (PMID 40870446, 2025). "Some extracellular proteins, including CCN3 and ECM1, have been suggested as stimulators of integrin/FAK for invasion and metastasis of cancer cells." (PMID 38355577, 2024). "In this study, we explored the prognostic value of DKK3, ECM-1 and TGFB1 using a bioinformatical approach through analysis of large publicly available datasets from The Cancer Genome Atlas Program (TGCA) and Pan-Cancer Atlas databases." (PMID 38855324, 2024). "Specifically, exosomal extracellular matrix protein 1 (ECM1) was found to promote progression and even metastatic invasion in most cancers." (PMID 38200509, 2024). "The 10-biomarker signature in this category additionally incorporating FABP5, C1RL, MMP9, ECM1, S100A7 and CF1, discriminated early-stage cancers from controls with an AUC of 0.92 (0.86–0.97)." (PMID 36807337, 2023). "In certain cancer types, the significant increase in MMP9 transcription can be observed in parallel with the upregulation of ECM1, suggesting that the ECM1–MMP9 axis is of great significance for tumorigenesis and progression." (PMID 36765767, 2023). "Therefore, ECM1 could be a selective target for cancer therapy." (PMID 36145166, 2022). "The study revealed that cancer-secreted extracellular matrix protein 1 (ECM1) induced Notch-mediated endothelial feedback and enhanced migration and invasion to promote cancer progression." (PMID 36017236, 2022). "Exosomal extracellular matrix protein 1 (ECM1) 87 and Alpha-2-HS-glycoprotein (AHSG) 88 respectively promote cancer progression and invasion in most tumors." (PMID 34234872, 2021). "By increasing the association between β-catenin and the MUC1 cytoplasmic tail, ECM1 regulated the EMT progression and cancer stem cell proliferation." (PMID 31335317, 2019). "Extracellular Matrix Protein 1 (ECM1) is a major component of the extracellular matrix, would stimulate the proliferation of endothelial cells and promotes angiogenesis and cancer progression." (PMID 28881838, 2017). "Extracellular matrix protein-1 (ECM1) induces cisplatin resistance via integrin αXβ2 and downstream activation of Akt/FAK/Rho signaling, leading to ABC sub-family G member 1 (ABCG1)-mediated enhancement of cancer stem-like traits." (PMID 41596584, 2026). "Indeed, all the genes were overexpressed in the CRC mutant compared to the KRAS WT cancer cell lines, except for DKK1 and ECM1." (PMID 40013338, 2025). "In three-dimensional (3D) culture models, co-culture of high ECM1-expression cancer cells (A8-ctrli, Hey-ctrli, A2780cis-ctrli, A2780-ECM1) with NFs formed more and larger spheroids than without NFs." (PMID 36145166, 2022).
cancer (continued). "Based on TCGA BLCA dataset, we found that CRYAB (AUC = 0.9326, P < 0.001), ECM1 (AUC = 0.6782, P = 0.009), CGNL1 (AUC = 0.9314, P < 0.001), and GPX3 (AUC = 0.8480, P < 0.001) are effective in distinguishing HGBC tissues and normal para-carcinoma tissues." (PMID 32292720, 2020). "To confirm the impact of altered ECM1, MBL2, BTD and RAB5C expression in existing clinical patient studies, we analysed four biomarker‐altered and non‐altered groups with a survival of 1084 patients in the pan‐cancer atlas and 2509 patients in the METABRIC data." (PMID 40545963, 2025). "However, co-culture of low ECM1-expression cancer cells (A8i, Heyi, A2780cisi, A2780-Vec) with NFs failed to induce more and larger spheroids compared than without NFs." (PMID 36145166, 2022). "In particular, we identified three new genes (ECM1, ATF5, and EOMES) with potential anti-cancer functions that may promote the understanding of the molecular mechanisms of HCC development and progression and potentiate the future clinical applications of 5hmC detection." (PMID 25517360, 2014). "Similarly, LA/DC-NK cells, rather than YL/DC-NK cells, could also generate remarkable cytotoxicity without restriction of ECM1 expression against primary cancer cells." (PMID 33910591, 2021). "Low, high, and moderate ECM1 mRNA levels were detected in one (A2780), two (Hey and HeyA8), and four (SKOV3, SKOV3ip1, OVCA429, and OVCA433) cancer cell lines, respectively, whereas no ECM1 mRNA was detected in HOSE cells." (PMID 34244494, 2021). "Moreover, an increased positive rate of ECM1 was observed in TSCC tissues rather than adjacent tissues by IHC, which was additionally verified in paired cancer adjacent tissues from 17 patients by RT-qPCR." (PMID 31335317, 2019).